COL4A3 (collagen type IV alpha 3 chain)
Diseases named in the same sentence as COL4A3 in open-access papers (continued):
Sharing a sentence is not in itself a finding about the gene and the disease.
Alport syndrome (continued). "A new form of digenic non-Mendelian inheritance of Alport syndrome, with coexisting mutations in COL4A3, COL4A4, or COL4A5 genes, has recently been described, simulating autosomal recessive inheritance (digenic mutations in trans) or autosomal dominant inheritance (mutations in in cis mode)." (PMID 33233744, 2020). "While pathogenic COL4A5 variants cause x-linked Alport syndrome and bi-allelic mutations in COL4A3 or COL4A4 cause the autosomal recessive form, the interpretation of the biological significance of rare pathogenic but heterozygous COL4A3 or COL4A4 mutations can be challenging." (PMID 31049720, 2020). "The aim of the current study was to examine the effects of MMF treatment on kidney function and on the phosphorylation status of renal proteins in COL4A3-deficient (COL4A3−/−) mice, which represent an in vivo, non-hypertensive model for the autosomal form of Alport syndrome." (PMID 25525413, 2014). "Mice with global deletion of the collagen type IV alpha 3 chain (Col4a3) develop glomerular injury that progresses to CKD and are a model of Alport syndrome." (PMID 38791164, 2024). "The members of the extracellular matrix structural constituent, COL4A3, COL4A4 and COL4A5, have been reported to be consistent with digenic inheritance and, together, lead to the occurrence of Alport syndrome." (PMID 35804365, 2022). "Recent advances in genetic analysis have enabled comprehensive and efficient screening of multiple genes including COL4A3, COL4A4, and COL4A5 for patients suspected as having Alport syndrome." (PMID 35211492, 2022). "Observed versus expected likelihood of Glycine substitutions in the COL4A5, COL4A3 and COL4A4 genes in Alport syndrome and Thin basement membrane nephropathy." (PMID 27627812, 2016). "Podocyte invasions occurred in Alport (Col4a3−/−), Myo1e−/− and Ptpro−/− mice and lucent regions of GBM, resembling sites of podocyte invasion, were seen in patients with Alport syndrome." (PMID 27725732, 2016). "The clinical features in Alport syndrome are explained because the COL4A5 and COL4A3/COL4A4 genes code for the collagen IV α5 chain, α3 and α4 chains which form a heterotrimer in the basement membranes of the glomerulus, cochlea and eye." (PMID 27627812, 2016). "Alport syndrome, which contained COL4A4 and COL4A3, was the only enriched term from the OMIM_DISEASE category listed in the chart." (PMID 25109818, 2014). "Some genes that can mimic ADPKD, such as COL4A3, COL4A4, and COL4A5 associated with Alport syndrome, were not standardly included as part of the analyses for individuals in these studies." (PMID 41509997, 2026). "While maternal carrier status for an X‐linked Alport syndrome gene variant (COL4A5) was disclosed, P/LP variants in COL4A3 or COL4A4 were not reported unless both partners had at least one variant." (PMID 40317772, 2025). "Podocyte damage in animal models of non-diabetic disease such as the Col4a3 knockout model of Alport Syndrome prone to lipotoxicity showed that empagliflozin was protective of lipotoxicity-induced podocyte apoptosis." (PMID 39950157, 2025). "Since the kidney cysts in Alport syndrome and the no-mutation-detected subtype of ADPKD are usually smaller and fewer than typical ADPKD, the role of COL4A3 and COL4A4 in tubular basement membrane might be only minor in the cystogenesis." (PMID 41450889, 2025). "In conclusion, we have reported for the first time two cases of X-linked Alport syndrome where the only structure affected by a decrease in COL4A5 immunolabeling was Bowman’s capsule and where neither COL4A3 nor COL4A4 could have thus been at cause." (PMID 38668984, 2024). "Although this study did not indicate a causal relationship between variants on the COL4A5/COL4A3 gene and familial IgAN, it illustrated that the mutations in the COL4A5/COL4A3 gene may cause a wide spectrum of diseases, not just Alport syndrome." (PMID 38202130, 2023).
Alport syndrome (continued). "However, another group of authors who conducted a similar analysis of a large cohort of patients with dominant forms of Alport syndrome (COL4A3 and COL4A4) before our study did not observe statistical differences between the sexes." (PMID 36013122, 2022). "However, the 2 most commonly affected genes (COL4A3 and COL4A4) have no extrarenal associations in AD Alport syndrome but are associated with hearing loss and ocular abnormalities in the much less common AR Alport syndrome." (PMID 40303230, 2025). "No COL4A3 staining was detected indicating that focal absence of α1.α1.α2(IV) does not lead to compensatory α3.α4.α5(IV) expression, in contrast to the continued expression of α1.α1.α2(IV) in response to absence of α3.α4.α5(IV) in some Alport syndrome patients." (PMID 24001601, 2014). "Genetic testing is now the gold standard investigation, with next-generation sequencing of COL4A3, COL4A4, and COL4A5 being recommended in patients with no family history of Alport syndrome." (PMID 41299396, 2025). "Overall, the commonest genes affected in FSGS are COL4A5 (XL Alport syndrome) and COL4A3 and COL4A4 (usually AD rather than the rare AR Alport syndrome) INF2, TRPC6 and ACTN4." (PMID 37578539, 2024).
renal failure (30 papers, 2010 to 2025). "Heterozygote carriers of frameshift/splicing variants in COL4A3/COL4A4 presented a higher risk of developing renal failure than those with missense variants in the glycine domains (p = 0.015)." (PMID 33369211, 2021). "Heterozygous carriers of frameshift/splicing variants in COL4A3/COL4A4 presented a higher risk of developing renal failure than those with missense variants in the glycine domains (p = 0.015)." (PMID 33369211, 2021). "Renal failure is less common, but recognised increasingly, with pathogenic heterozygous COL4A3 or COL4A4 variants." (PMID 33854215, 2021). "This is in line with a genotype-phenotype correlation postulated for COL4A3 as nonsense or larger rearrangement variants lead to a shortening of the protein and are associated with a younger age at renal failure (<20 years)." (PMID 29946535, 2018). "The age at onset of renal failure was also the same for homozygous and for compound heterozygous COL4A3 and COL4A4 mutations (21.5 ± 7.2, 95%CI 17.2–25.9, n = 13; and 21.8 ± 7.0, 95% CI 19.8 to 23.7, n = 52)." (PMID 27627812, 2016). "The age at onset of renal failure was known for some homozygous or compound heterozygous COL4A3 (n = 35) and COL4A4 (n = 25) pathogenic mutations where both variants were known." (PMID 27627812, 2016). "Furthermore, in contrast to previous studies suggesting that PKD1 and PKD2 are the most common genetic causes of kidney failure, our findings indicate that among Bedouins, COL4A3 variants are the predominant genetic etiology." (PMID 40303201, 2025). "Alport disease, which is a familial nephropathy marked by focal splitting, thinning, and regional thickening of the GBM and leads to renal failure, is caused by mutations in either the COL4A3, COL4A4, or COL4A5 genes encoding the collagen α3(IV), α4(IV), and α5(IV) protein chains, respectively." (PMID 21915268, 2011). "However, in all these conditions, persistent microscopic haematuria and a family history or microscopic haematuria or kidney failure may be present, suggesting an underlying disease-causing COL4A3–5 variant." (PMID 35260866, 2022). "By incorporating genetic markers such as variants in COL4A3, COL4A4, and COL4A5, our study design can address the variable progression rates from diagnosis to renal failure." (PMID 40165927, 2025). "In addition, mutations in COL4A3 have been reported in patients with focal segmental glomerulosclerosis, a condition in which scar tissue progresses on the glomeruli, which might result in proteinuria and renal failure." (PMID 38926794, 2024). "Systemic deletion of Col4a3 (CMV-Crepos; Col4a3L/L) phenocopied the total body knock out of Col4a3 (Col4a3KO), demonstrating a median survival of 28.1 wk and death due to renal failure." (PMID 38561223, 2024). "In conclusion, this study confirms that mono-allelic COL4A3 or COL4A4 variants are associated with a wide clinical and pathological spectrum of kidney disease, ranging from isolated microscopic hematuria to kidney failure." (PMID 36925663, 2023). "This study confirms the wide phenotypic spectrum associated with mono-allelic COL4A3/COL4A4 variants, extending from isolated microscopic hematuria to kidney failure with high intra- and interfamilial variability." (PMID 36925663, 2023). "Heterozygous variants in COL4A3 and COL4A4 were found in 14 families for a total of 34 patients: of them, 96% presented with microhematuria and 8 out 34 (24%) developed renal failure at a mean age of 65 years." (PMID 33369211, 2021). "Cpd G (100 mg/kg), or vehicle, were administered to Col4a3 KO mice daily, by oral gavage, starting at 4 weeks of age when mice first present with signs of renal insufficiency." (PMID 34341345, 2021). "Untreated COL4A3 −/− mice die from renal failure typically after 66 to 71 days, whereas the normal life span of WT mice is 565 days." (PMID 25525413, 2014).
renal failure (continued). "A model of Alport disease has been created in mice through the deletion of the Col4a3 gene, and these animals die of renal failure 2–4 months after birth with the same glomerular defects as those seen in Alport patients." (PMID 21915268, 2011). "In patients with heterozygous pathogenic variants in the COL4A3/A4, while most frequently there is only uniform thinning of the GBM, some patients develop renal features reminiscent of typical AS, but with a much later age for the onset of kidney failure." (PMID 37761826, 2023). "Surprisingly, we found slight differences between the sexes in the cases affected by mutations in COL4A3/4 with a borderline p value (p = 0.03), and stronger statistically significant differences between the sexes considering ESKD and renal failure and excluding CRD as events." (PMID 36013122, 2022). "Nonsense COL4A3 and COL4A4 mutations were also associated with a younger age at renal failure." (PMID 27627812, 2016). "This study confirmed that two COL4A3 or COL4A4 mutations resulted in earlier onset renal failure than one or no severe mutations." (PMID 27627812, 2016). "Individuals with at least one direct nonsense COL4A3 or COL4A4 mutation also developed renal failure at a younger age than those with none." (PMID 27627812, 2016). "Alport disease in humans, which usually results in proteinuria and kidney failure, is caused by mutations to the COL4A3, COL4A4, or COL4A5 genes, and absence of collagen α3α4α5(IV) networks found in mature kidney glomerular basement membrane (GBM)." (PMID 23236390, 2012). "Regarding renal failure, our results showed that adverse events associated with renal function deterioration (ESKD and CRD) and renal replacement therapy (dialysis, renal transplant) were accumulated among the 30–70-year-old patients with deleterious mutations in COL4A3/4." (PMID 36013122, 2022). "For the COL4A3 and COL4A4 genes, age at renal failure occurred sooner with two non-missense variants (p = 0.08, and p = 0.01 respectively)." (PMID 27627812, 2016). "Eight (24%) of the 34 heterozygous COL4A3 and COL4A4 carriers developed renal failure at a mean age of 57 years, with a significantly lower risk than hemizygous COL4A5 or double heterozygous COL4A3/COL4A4 carriers (p < 0.01), but not different from that of the heterozygous COL4A5 females (p = 0.6)." (PMID 33369211, 2021).
focal segmental glomerulosclerosis (27 papers, 2014 to 2025). A renal disorder characterized by sclerotic lesions in the glomeruli. "Pathogenic variants in COL4A4 or COL4A3 genes were frequently found in patients with focal segmental glomerulosclerosis (FSGS)." (PMID 36982595, 2023). "Based on the relevant publications, focal segmental glomerulosclerosis has emerged as a frequent histological finding in kidney biopsy specimens of patients with heterozygous disease-causing COL4A3/A4 variants, including in patients with AS." (PMID 37761826, 2023). "Heterozygous mutations in COL4A4 or COL4A3 genes are frequent among patients with microscopic hematuria of glomerular origin and have been confirmed in patients with focal segmental glomerulosclerosis." (PMID 36982595, 2023). "Familial segregation of microhematuria and proteinuria can result from defects in one of the COL4A3/A4/A5 genes or in genes causing hereditary focal and segmental glomerulosclerosis or MYH9-related disorders." (PMID 36553470, 2022). "Using whole-exome sequencing, we have recently reported that pathogenic variants in the COL4A3/A4/A5 genes are the leading single gene causes (∼5%) of focal and segmental glomerulosclerosis (FSGS), a histopathologic entity representing diverse causes." (PMID 33851121, 2021). "Rare missense variants in COL4A3/A4/A5 were identified in disease cohorts, including a local focal segmental glomerulosclerosis (FSGS) cohort and publicly available disease databases, in which they are categorized as pathogenic or benign based on clinical criteria." (PMID 33851121, 2021). "In addition, recent studies support that the COL4A3 gene is a newly discovered pathogenic gene related to focal segmental glomerulosclerosis (FSGS)." (PMID 30881523, 2019). "Τargeted genetic sequencing in a 6-year-old with steroid-resistant nephrotic syndrome and biopsy findings of focal segmental glomerulosclerosis (FSGS) revealed a novel COL4A3 pathogenic variant (p.Arg341His)." (PMID 41562995, 2025). "Among the most common pathogenic variants were COL4A3, COL4A4, COL4A5, and other genes that are implicated in focal segmental glomerulosclerosis." (PMID 38993907, 2023). "Heterozygous COL4A3 or COL4A4 variants, or heterozygous COL4A5 in women can present with a range of histological and phenotype features variably, including hematuria, proteinuria, focal segmental glomerulosclerosis, and chronic kidney disease." (PMID 37180518, 2023). "Recent findings by us and others showed that about 50% of patients with COL4A3/COL4A4 heterozygous mutations, a prevalent cause of familial microscopic hematuria due to TBMN, develop proteinuria with secondary focal segmental glomerulosclerosis (FSGS), after their third decade of life." (PMID 28334007, 2017). "Pathogenic variants in the COL4A3, COL4A4, and COL4A5 genes lead to collagen IV (COL4) nephropathies, including Alport syndrome (AS), thin basement membrane nephropathy, and familial forms of focal segmental glomerulosclerosis (FSGS)." (PMID 39588246, 2024). "The clinical phenotypes of heterozygous mutations in COL4A3 and COL4A4 are heterogeneous, and can cause autosomal dominant AS (ADAS), thin basement membrane nephropathy (TBMN), focal segmental glomerulosclerosis (FSGS) and benign familial hematuria (BFH)." (PMID 28542346, 2017). "In focal segmental glomerulosclerosis (FSGS) patients, COL4A3 and COL4A4 were frequently not tested, resulting in a missed molecular diagnosis in some patients and inappropriate genetic counseling." (PMID 36925663, 2023).
Nephropathy (27 papers, 2012 to 2025). A nonspecific term referring to disease or damage of the kidneys. "We report a case of a child with SRNS and biopsy findings of FSGS who was ultimately diagnosed with a type IV collagen-related nephropathy after identification of a rare COL4A3 variant." (PMID 41562995, 2025). "The identification of a rare COL4A3 variant, supported by electron microscopy findings, led to the diagnosis of a type IV collagen-related nephropathy and justified the withdrawal of ineffective immunosuppressive treatment." (PMID 41562995, 2025). "Alport syndrome (AS) is a clinically heterogeneous nephropathy caused by pathogenic variants in collagen IV genes (COL4A3, COL4A4, COL4A5) with a prevalence of 1:5.000." (PMID 35260866, 2022). "Diseases, such as thin basement membrane nephropathy (TBMN), FSGS, and Alport syndrome (AS), which are caused by COL4A3–5 gene mutations, have been termed as type IV collagen-related nephropathies." (PMID 33305316, 2021). "Type IV collagen-related nephropathies are a genetically diverse group of inherited kidney disorders caused by mutations in the collagen type IV alpha-3 (COL4A3), alpha-4 (COL4A4) or alpha-5 (COL4A5) genes, which encode essential components of the glomerular basement membrane (GBM)." (PMID 41562995, 2025). "Furthermore, GWAS of the T1D Nephropathy Collaborative Research Initiative of European descent identified COL4A3 as one of the predisposing loci based on albuminuria and renal function." (PMID 36633903, 2023). "Our findings may help further understand the pathogenesis of type IV collagen-related nephropathy caused by COL4A3 mutation, and may provide a reference for clinical practice in the future." (PMID 33305316, 2021). "For this reason, we need to change the definition of AS to include all cases with nephropathy caused by COL4A3, COL4A4, or COL4A5 gene variants and eliminate the disease entity of TBM; this will allow patients to avoid missing the opportunity to start appropriate treatment as early as possible." (PMID 30128941, 2019). "In addition, we also recommended the new classification of collagen IV nephropathies, which may be a benefit to the diagnosis, target drug treatment, and management of patients with COL4A3/COL4A4 mutations." (PMID 33159707, 2020). "In addition, together with previous studies, we also recommended the new classification of collagen IV nephropathies, which may be a benefit to the diagnosis, target drug treatment, and management of patients with COL4A3/COL4A4 mutations." (PMID 33159707, 2020). "While COL4A5 gene variants cause X-linked AS, mutations in COL4A3 or COL4A4 genes (both located on chromosome 2) are associated with autosomal recessive AS, autosomal dominant AS, and thin basement membrane nephropathy." (PMID 41306271, 2025). "Patients from Family 2 (P4, P5) and Family 3 (P6–P8) carried COL4A3 variants classified as either pathogenic or VUS, supporting collagen IV-related nephropathies." (PMID 41288877, 2025). "Variants in CASZ1 and SHROOM3 were associated with microalbuminuria and UACR, and DPEP1 along with COL4A3 were common for kidney damage and UACR." (PMID 37446387, 2023). "Variants in CASZ1 and SHROOM3 were common for microalbuminuria and UACR, and DPEP1 along with COL4A3 were common for kidney damage and UACR (p < 0.001)." (PMID 37446387, 2023). "Among them, the SNP variant rs55703767, responsible for a mutation in the collagen type IV alpha 3 chain (COL4A3), was the variant with the strongest association with kidney damage and CKD progression." (PMID 35628528, 2022). "Results after re-sequencing of 103 samples with mutations in COL4A3 or COL4A4 genes and thin basement membrane nephropathy." (PMID 22319602, 2012).